RNU2-20P (RNA, U2 small nuclear 20, pseudogene)
Gene: Small nuclear RNA gene on chromosome 3 (168,475,198 to 168,475,388, forward strand). Ensembl gene ENSG00000222357.
Homologues: Orthologues: chimpanzee U2 (99% identical), macaque U2 (97% identical), guinea pig U2 (72% identical), mouse Gm23628 (65% identical), rabbit U2 (35% identical), rat LOC120098022 (24% identical). Paralogues in human: U2 (84% identical), RNU2-2 (83% identical), RNU2-3P (83% identical), U2 (82% identical), RNU2-59P (82% identical), RNU2-4P (81% identical), RNU2-26P (81% identical), RNU2-36P (80% identical), RNU2-57P (80% identical), RNU2-6P (80% identical), RNU2-32P (78% identical), RNU2-23P (77% identical), and 66 more.